FERMT1 (FERM domain containing kindlin 1)
Diseases named in the same sentence as FERMT1 in open-access papers (continued):
Sharing a sentence is not in itself a finding about the gene and the disease.
FERMT1 also shares sentences with these, for which no sentence is quoted: esophageal cancer (4 papers); cutaneous squamous cell carcinoma (3); lung adenocarcinoma (3); non-small cell lung carcinoma (3); squamous cell carcinoma (3); breast tumors (2); inflammatory bowel disease (2); intestinal disease (2); lung squamous cell carcinoma (2); acute myeloid leukemia (1); Atrophy (1); bone metastasis (1); Bradycardia (1); breast adenocarcinoma (1); bullous skin disease (1); colon adenocarcinoma (1); Crohn disease (1); genetic disorder (1); head and neck squamous cell carcinoma (1); ileitis (1); Kyphosis (1); large cell lung cancer (1); lung (1); metastatic tumors (1); neuropathic pain (1); Onset (1); oral cancer (1); pancreatic adenocarcinoma (1); prostate tumors (1); scoliosis (1).
A further 5 diseases each share a sentence with FERMT1 in 1 paper.